C5AR1 (complement C5a receptor 1)
Diseases named in the same sentence as C5AR1 in open-access papers (continued):
Sharing a sentence is not in itself a finding about the gene and the disease.
glioma (8 papers, 2018 to 2024). A benign or malignant brain and spinal cord tumor that arises from glial cells (astrocytes, oligodendrocytes, ependymal cells). "Analysis of CGGA data showed that C5aR1 expression increased with increasing glioma grade and that C5aR1 overexpression was associated with poor prognosis in patients with glioma, as indicated by the low survival rate of patients with high C5aR1 expression." (PMID 39368999, 2024). "The results confirmed that C5aR1 was upregulated specifically in glioma tissue, especially in GBM tissue." (PMID 39368999, 2024). "To investigate the role of C5aR1 in glioma pathogenesis, we examined its expression in glioma tissue using data from the TCGA database and the CGGA." (PMID 39368999, 2024). "According to the analysis of TCGA data, C5aR1 was significantly upregulated in low-grade glioma (LGG) tissue (n = 518) and GBM tissue (n = 163) compared to normal brain tissue (n = 207)." (PMID 39368999, 2024). "Using machine learning approaches based on paired MRI and RNA sequencing data, our results show that radiomics MRI features can be used to build models that can noninvasively predict C5aR1 expression and the prognosis of patients with high-grade glioma." (PMID 37760630, 2023). "We identified two gene signatures composed of SLC32A1/MSR1 and SYT5/C5AR1 gene combinations whose expression alone strongly correlated with this subgroup of IDH-WT gliomas." (PMID 33059718, 2020). "Overall, we envisage that the lower expression of C5AR1 in NL gliomas, by impacting negatively on MSR1-expressing M2 phenotype macrophages and positively on NK and CD4+/CD8+ T cells, favors anti-inflammatory and anti-tumoral cell signaling cascades." (PMID 33059718, 2020). "Among the top-scored L–R autoc-rine pairs, there was an interaction between RPS19 and C5AR1, detected in all the patients with glioma tested (n = 39, P = 6.68 · 10−76)." (PMID 33155039, 2020). "We further divided the glioma patients from Yancheng Clinical College of Xuzhou Medical University into the C5aR1 high- and low-expression groups and analyzed the correlations between the C5aR1 expression level and the clinicopathological parameters of the glioma patients." (PMID 39368999, 2024). "In the present study, we observed significant upregulation of C5aR1 in glioma tissue." (PMID 39368999, 2024). "In this study, we suggest a potential role for C5aR1 as a biomarker of glioma prognosis." (PMID 37760630, 2023). "The identification of C5AR1 and MSR1 overexpression in the OT group may suggest differences in the NL vs OT glioma tumor-associated immune microenvironment." (PMID 33059718, 2020). "To determine whether the death of glioma cells induced by C5aR1 knockdown is due primarily to ferroptosis, we performed TEM, which showed that C5aR1 knockdown caused extensive changes in mitochondria, such as mitochondrial shrinkage, loss of cristae, and rupture of the outer membrane." (PMID 39368999, 2024). "Analysis of the CGGA-325 dataset revealed a significant correlation between C5aR1 expression and ERK1/2 pathway activity in gliomas." (PMID 39368999, 2024). "In conclusion, our findings suggest that C5aR1 inhibits ferroptosis in GBM cells and promotes MettL3-dependent GPX4 expression through ERK1/2, thereby promoting glioma progression." (PMID 39368999, 2024). "This retrospective study aimed to assess its prognostic value in high-grade glioma (HGG) and predict C5aR1 expression using a radiomics approach." (PMID 37760630, 2023). "Using the first CGGA dataset, 14 samples were classified as NL gliomas with both SLC32A1/MSR1 and C5AR1/SYT5 gene signatures vs 263 OT samples." (PMID 33059718, 2020). "Further characterization of these gene signatures indicated that the C5AR1 and MSR1 genes were significantly overexpressed in the OT cluster and, in general, in higher-grade gliomas." (PMID 33059718, 2020).
glioma (continued). "A machine learning-based approach identified C5AR1/SYT5 and MSR1/SLC32A1 signatures which were able to discriminate NL IDH-WT gliomas with high sensitivity and specificity in various glioma expression datasets." (PMID 33059718, 2020). "However, C5aR1 has not been studied as thoroughly in glioma." (PMID 39368999, 2024).
lupus (8 papers, 2014 to 2025). "For example, in a model of lupus-like chronic graft-versus-host disease (GvHD), genetic or pharmacological ablation of C5aR1 in CD4+ T cells protected from the generation and expansion of TFH cells, GC B cells, and autoantibodies." (PMID 35958588, 2022). "To identify the upstream and downstream relationships of these upregulated genes (C1q, C3, C3aR1, C5aR1, CR3, and CR4), we performed KEGG pathway analysis using the lupus mouse microarray database." (PMID 34433493, 2021).
cognitive decline (7 papers, 2022 to 2025). "Genetic ablation of C5aR1 in the Arctic mouse model of AD results in a protection from cognitive decline and from loss of neuronal complexity in the CA129 and CA3 region of the hippocampus at 10 months of age." (PMID 38278523, 2024). "Similarly, C5a and C5aR1 overexpression in an AD mouse model resulted in accelerated cognitive decline." (PMID 40637922, 2025). "In two mouse models of AD, pharmacologic inhibition of the C5a receptor (C5aR1) with PMX205 reduced amyloid plaque accumulation, attenuated activation of microglia and astrocytes, and protected mice against hippocampal synaptic loss and cognitive decline." (PMID 35820938, 2022). "Using this model, our previous work demonstrated that amyloid is a necessary but not the sole driver of cognitive decline, as ablation of C5aR1 prevented loss of neuronal complexity and cognition." (PMID 35820938, 2022). "The results presented here show that pharmacologic inhibition of C5aR1 in adult mice with substantial amyloid plaque load can also protect against hippocampal-dependent spatial memory deficits, highlighting its potential as a therapeutic target to slow or ameliorate cognitive decline in adults." (PMID 39147742, 2024). "Furthermore, we observed accelerated cognitive decline in the ArcC5a+, consistent with the hypothesis that C5a–C5aR1 signaling is deleterious in combination with amyloid pathology." (PMID 35820938, 2022). "Pharmacological inhibition of C5aR1 using the antagonist PMX205 has consistently demonstrated therapeutic benefit in transgenic AD models such as Tg2576 and Arctic48, where it reduced amyloid burden, gliosis, and cognitive decline." (PMID 41398960, 2025). "Previously, our lab has demonstrated that genetic ablation of C1q or C5aR1, as well as pharmacological inhibition with the C5aR1 inhibitor PMX205, reduces neuroinflammation and/or pathology in AD models and rescues cognitive decline." (PMID 37726739, 2023). "We previously reported that ablation of C5aR1 in Arc mice prevents memory deficits assessed with the OLM test at 10 months of age, suggesting that binding of C5a to C5aR1 induces responses that contribute to the cognitive decline observed in this model." (PMID 35820938, 2022).
Insulin resistance (7 papers, 2013 to 2025). Increased resistance towards insulin, that is, diminished effectiveness of insulin in reducing blood glucose levels. "Furthermore, adipocytes express C3aR and C5aRs (C5aR1 and C5aR2), which, via their corresponding ligands (C3a and C5a), increase the local and systemic inflammation along with increasing insulin resistance." (PMID 40904461, 2025).
meningococcal infection (7 papers, 2018 to 2025). Infections with bacteria of the species neisseria meningitidis. "This outcome provides a clear demonstration of the therapeutic benefit of the use of C5aR1-specific inhibitors to improve the outcome of invasive meningococcal disease." (PMID 29362231, 2018). "In clear contrast, C5ar1−/− mice resisted invasive meningococcal infection and cleared N. meningitidis more rapidly than wild-type (WT) animals." (PMID 29362231, 2018). "On the other hand, while C5-deficient mice displayed higher susceptibility to Neisseria meningitidis infection, the lack of C5aR1 contributed to a favourable outcome ameliorating inflammatory cytokine response more rapidly than wild-type mice." (PMID 31687410, 2019).
pulmonary fibrosis (7 papers, 2017 to 2025). Chronic progressive interstitial lung disorder characterized by the replacement of the lung tissue by connective tissue, leading to progressive dyspnea, respiratory failure, or right heart failure. "Although C5a/C5aR1 signaling has been implicated in pulmonary fibrosis, its precise role in regulating FMT within the lung microenvironment remains unclear." (PMID 40867551, 2025). "Our study demonstrated that the C5a/C5aR1–calcium signaling is activated in lung fibroblasts via pulmonary fibrosis models and lung fibroblasts stimulated in vitro." (PMID 40867551, 2025). "To investigate the therapeutic potential of C5a/C5aR1 signaling in established pulmonary fibrosis, we used PMX53 once a day from day 7 post-modeling." (PMID 40867551, 2025). "C5a/C5aR1 signaling is recognized as a key mediator of inflammation and fibrosis in pulmonary fibrosis." (PMID 40867551, 2025). "The C5a/C5aR1 axis activates the TGFβ/Smad pathway in epithelial injury of pulmonary fibrosis, and the activation of NO is blocked after silencing the expression of C3 and C5." (PMID 33869223, 2021). "The expression of C5a and C5a receptor 1 (C5aR1) increased in the lung tissues of IPF patients and mice with pulmonary fibrosis." (PMID 40867551, 2025). "Therefore, targeting the C5a/C5aR1–calcium–ACSL4 axis could effectively ameliorate fibrotic progression by reducing fibroblast activation and migration, potentially offering a novel therapeutic strategy for pulmonary fibrosis treatment." (PMID 40867551, 2025). "However, the relationship between C5a/C5aR1 signaling and ACSL4 in pulmonary fibrosis has not been elucidated." (PMID 40867551, 2025).
vasculitis (7 papers, 2020 to 2025). "The C5a ligand and its receptor C5aR1 play a central role in the pathogenesis of anti-neutrophil cytoplasmic antibody (ANCA)–associated vasculitis which is characterized by blood vessel inflammation resulting in tissue destruction." (PMID 36015147, 2022). "The anti-human C5/C5a antibody MEDI7814 neutralizes the C5aR1 and C5aR2 receptors; a C5aR antagonist, Avacopan (CCX168), was approved in 2022 for use in ANCA vasculitis." (PMID 38458648, 2024).
amyloid (6 papers, 2022 to 2025). "The shift of tenascin signaling from OPCs to astrocytes in the Arc-PMX205 cells, in addition to FGF signaling, suggests that inhibition of C5aR1 promotes a return to homeostatic state in astrocytes exposed to amyloid pathology." (PMID 39147742, 2024). "Assessment of RNA expressed by other brain cell types supports extensive communication between cell types that is also modulated by C5aR1 in the context of amyloidosis." (PMID 39147742, 2024). "Not all AD-associated genes were altered, indicating differences in genes whose expression change in response to amyloid plaque deposition and genes whose expression change in response to C5a–C5aR1 signaling, the latter of which may play an essential role in worsening AD cognitive performance." (PMID 35820938, 2022).
cervical cancer (6 papers, 2020 to 2025). A primary or metastatic malignant neoplasm involving the cervix. "Using a syngeneic mouse model of cervical cancer, they demonstrated that C5a receptor (C5aR) antagonism or C5aR1 genetic deficiency controlled tumour growth to a similar extent to paclitaxel." (PMID 36650365, 2023). "Our work and that of others has previously shown that the expression of C5aR1 is higher in tumours compared to normal tissues in several cancers such as gastric, colorectal, and cervical cancer." (PMID 40695778, 2025).
coronary artery disease (6 papers, 2015 to 2025). "A study published in 2015 showed a significant association between a C5aR1 polymorphism (rs10853784) and coronary artery disease in a Han population from Xinjiang, China." (PMID 41155225, 2025). "Broadly, C5aR1 expression and binding on atherosclerotic lesions cause local inflammatory responses that exert destructive effects on blood vessels, contributing to coronary artery disease and the possible development of future myocardial infarction." (PMID 41155225, 2025). "However, There are unknown associations between the SNPs of C5aR1 gene and coronary artery disease (CAD)." (PMID 25924896, 2015).
diabetic nephropathy (6 papers, 2021 to 2025). "C5a also mediates cellular senescence in diabetic nephropathy, and the C5aR1 inhibitor PMX53 attenuates cellular senescence." (PMID 39835101, 2024). "Complement C5a and its receptor C5aR1 are upregulated early in the disease process and prior to manifesting kidney injury in several experimental models of diabetic nephropathy." (PMID 38069385, 2023).
glioblastoma (6 papers, 2019 to 2025). The most malignant astrocytic tumor (WHO grade IV). "TCGA analysis showed that C5aR1 mRNA levels are strongly correlated with a UPR signature in various types of tumours including glioblastoma, colorectal, ovarian and prostate cancers." (PMID 40695778, 2025). "TCGA analysis indicated that C5aR1 mRNA levels were significantly correlated with hypoxia signatures in glioblastoma, colorectal and prostate cancer, suggesting that C5aR1 expression may be increased in the hypoxic environment of tumours." (PMID 40695778, 2025).
influenza (6 papers, 2012 to 2024). An acute viral infection of the respiratory tract, occurring in isolated cases, in epidemics, or in pandemics; it is caused by serologically different strains of viruses (influenzaviruses) designated A, B, and C, has a 3-day incubation period, and usually lasts for 3 to 10 days. "In the current study, we use C5ar1−/− mice to determine the functional role of these interactions in the development of secondary acute pneumococcal OM following influenza infection." (PMID 24740152, 2014).
ischemic stroke (6 papers, 2013 to 2023). A stroke disorder caused by obstruction of blood flow to the brain, due to thrombotic (local blood clot formation) or embolic (due to a blood clot or other material traveling from another site) event. "However, a neuroprotective effect has been observed in C5aR1-deficient mice or in mice treated with a C5aR1 antagonist after ischemic stroke." (PMID 32174916, 2020). "In general, this study elucidated the mechanism of GHI against ischemic stroke by inhibiting inflammation and highlighted the potential important role of C5AR1 in ischemic stroke." (PMID 35387346, 2022). "C5ar1 (CD88) has been identified as an important potential therapeutic target for regulating inflammation in ischemic stroke." (PMID 35387346, 2022). "In this study, the inhibition of inflammation and targeting C5AR1 was identified as the key process in the long-term repair of GHI in ischemic stroke." (PMID 35387346, 2022). "Our study highlighted the benefits of inhibition of inflammation and targeting C5AR1 in the long-term repair of GHI in ischemic stroke." (PMID 35387346, 2022). "Collectively, cAMP/PKA, IκB/NF-κB, and Caspase 3 signaling pathways mediated by TLR4 and C5aR1 were identified to be essential for the inflammatory response and cell apoptosis in ischemic stroke of MCAO/R-exposed rats." (PMID 33633530, 2021). "It has been demonstrated that C5aR1 participated in the pathological mechanism of brain injury after ischemic stroke." (PMID 33633530, 2021). "C5a treatment induced neuronal apoptosis under OGD conditions, while C5aR1 deficiency prevented neurons from OGD-induced apoptosis, suggesting that inhibiting the interaction between C5a and C5aR1 was neuroprotective in the acute phase of ischemic stroke." (PMID 31011487, 2019). "Future studies should allocate more effort to elucidate the role of C5aR1 at the later stage of cerebral ischemia, which provides new insights into potential strategies targeting C5aR1 during ischemic stroke." (PMID 31011487, 2019). "Although the time course of C5aR1 expression was examined and its detrimental role at the early stage of ischemic stroke was demonstrated, the role of C5aR1 in the recovery process has not yet been explored." (PMID 31011487, 2019). "However, the effect of anti-C5 monoclonal antibodies and C5aR1 antagonists in ischemic stroke is limited." (PMID 31011487, 2019). "Increased C5aR1 expression was reported in Huntington disease, allergic encephalomyelitis, pyogenic granulomas of human skin, the CNS during inflammation, amyotrophic lateral sclerosis, closed head injury, and ischemic stroke." (PMID 31011487, 2019). "C5aR1 is primarily (although not exclusively) expressed on immune cells, and as such, has been implicated in proinflammatory signaling in numerous disorders including ischemic stroke and spinal cord injury." (PMID 37308987, 2023). "Thus, GHI provided obvious neuroprotection through inhibition of C5AR1 in ischemic stroke." (PMID 35387346, 2022). "Similarly, pre- or posttreatment with the C5aR1 antagonist AcF, also known as PMX53, reduced cerebral infarct volume at 24 hours of ischemic stroke in mice." (PMID 31011487, 2019). "TLR4 and C5aR1 contributed to inflammation and apoptosis via activating cAMP/PKA/I-κB/NF-κB signaling during cerebral I/R, suggesting that this signaling pathway may be a potent therapeutic target in ischemic stroke." (PMID 33633530, 2021).
endothelial dysfunction (5 papers, 2018 to 2025). In vascular diseases, endothelial dysfunction is a systemic pathological state of the endothelium (the inner lining of blood vessels) and can be broadly defined as an imbalance between vasodilating and vasoconstricting substances produced by (or acting on) the endothelium. "Activation of C5aR1 by its ligand C5a amplifies inflammation through crosstalk with TLR signaling, leading to enhanced NF-κB activation, cytokine release, and endothelial dysfunction." (PMID 41294830, 2025).
injury (5 papers, 2008 to 2023). Damage inflicted on the body as the direct or indirect result of an external force, with or without disruption of structural continuity. "This may indicate that activation of the C5a/C5aR1 axis is an important control mechanism for AM survival in the airways since C5aR1-induced apoptosis of AMs has been described in an acute lung injury model." (PMID 28931049, 2017).
pneumonia (5 papers, 2020 to 2023). An acute, acute and chronic, or chronic inflammation focally or diffusely affecting the lung parenchyma, caused by an infection in one or both of the lungs (by bacteria, viruses, fungi, or mycoplasma.). "The use of anti-C5aR1 to reduce C5a-C5aR1 signaling resulted in a reduction in pneumonia and extended animal survival." (PMID 35204727, 2022).